TEAD1 (TEA domain transcription factor 1)
Description:
Transcription factor which plays a key role in the Hippo signaling pathway, a pathway involved in organ size control and tumor suppression by restricting proliferation and promoting apoptosis. The core of this pathway is composed of a kinase cascade wherein MST1/MST2, in complex with its regulatory protein SAV1, phosphorylates and activates LATS1/2 in complex with its regulatory protein MOB1, which in turn phosphorylates and inactivates YAP1 oncoprotein and WWTR1/TAZ. Acts by mediating gene expression of YAP1 and WWTR1/TAZ, thereby regulating cell proliferation, migration and epithelial mesenchymal transition (EMT) induction. Binds specifically and cooperatively to the SPH and GT-IIC 'enhansons' (5'-GTGGAATGT-3') and activates transcription in vivo in a cell-specific manner. The activation function appears to be mediated by a limiting cell-specific transcriptional intermediary factor (TIF). Involved in cardiac development. Binds to the M-CAT motif.
Synonyms: TEAD-1; TCF-13; TCF13; TEF-1; AA; NTEF-1; REF1
Tractability: Small molecule: a structure with a bound ligand is known; a high-quality ligand is known; it has a binding pocket of medium quality. PROTAC: ubiquitination databases record sites on it; its protein half-life has been measured; a small molecule that binds it is known.
Target class: Transcription factor
Chemical probes: GNE-7883 (high quality), MYF-01-037 (high quality), VT103 (high quality), VT104 (high quality)
Gene: Protein-coding gene on chromosome 11 (12,674,421 to 12,944,737, forward strand). Ensembl gene ENSG00000187079.
Subcellular location: Nucleus
Subcellular location (Human Protein Atlas): Nucleoplasm
Pathways (Reactome):
Gene expression (Transcription): RUNX3 regulates YAP1-mediated transcription; YAP1- and WWTR1 (TAZ)-stimulated gene expression
Developmental Biology: EGR2 and SOX10-mediated initiation of Schwann cell myelination
Immune System: Regulation of PD-L1(CD274) transcription
Gene Ontology:
Molecular function: DNA-binding transcription factor activity; DNA-binding transcription factor activity, RNA polymerase II-specific; protein binding; RNA polymerase II cis-regulatory region sequence-specific DNA binding; sequence-specific double-stranded DNA binding; DNA binding; DNA-binding transcription activator activity, RNA polymerase II-specific
Biological process: hippo signaling; positive regulation of cell growth; positive regulation of DNA-templated transcription; positive regulation of miRNA transcription; positive regulation of transcription by RNA polymerase II; protein-containing complex assembly; embryonic organ development; regulation of transcription by RNA polymerase II; regulation of DNA-templated transcription
Cellular component: nucleoplasm; nucleus; TEAD-YAP complex; chromatin; transcription regulator complex
Genetic constraint (gnomAD): Loss-of-function variants: 9 observed, 56.98 expected, observed/expected ratio (o/e) 0.16, 90% interval 0.094 to 0.28. The upper end of that interval is the gene's LOEUF score, 0.28, which puts it in group 1 of 6, group 1 being the genes least tolerant of losing a copy. Missense variants: 384 observed, 558.52 expected, observed/expected ratio (o/e) 0.69, 90% interval 0.63 to 0.75. Synonymous variants: 200 observed, 196.74 expected, observed/expected ratio (o/e) 1.02, 90% interval 0.9 to 1.14.
Homologues: Orthologues: chimpanzee TEAD1 (99% identical), macaque TEAD1 (99% identical), pig TEAD1 (99% identical), rabbit TEAD1 (99% identical), guinea pig TEAD1 (99% identical), rat Tead1 (99% identical), mouse Tead1 (96% identical), dog TEAD1 (95% identical), tropical clawed frog tead1 (92% identical), zebrafish tead1b (80% identical), Drosophila melanogaster sd (59% identical). Paralogues in human: TEAD4 (76% identical), TEAD3 (71% identical), TEAD2 (66% identical).
Diseases named in the same sentence as TEAD1 in open-access papers:
TEAD1 is named in the same sentence as 130 diseases in open-access papers, as found by Europe PMC text mining. Sharing a sentence is not in itself a finding about the gene and the disease. The quoted sentences say what the papers report.
gastric cancer (17 papers, 2017 to 2025). A primary or metastatic malignant neoplasm involving the stomach. "In addition, over-activated TEAD1 upregulates miR-222 expression via physically binding to its promoter in gastric cancer cells, and a DNA damaging agent can cause dysregulation of miRNA expression at the transcriptional level." (PMID 28743280, 2017). "knockdown of TEAD1 has been shown to suppress cell proliferation in gastric cancer, conversely its overexpression enhances cell proliferation, migration and invasion in pancreatic cancer." (PMID 40539054, 2025). "Research has reported that TEAD1 is up-regulated in gastric cancer and regulated negatively by miR-4269." (PMID 34738862, 2021). "Of note, miR-4269 has been demonstrated to retard gastric carcinoma by negatively modulating TEAD1/4." (PMID 32484209, 2020). "SIRT1 was reported to delactylate YAP and TEAD1 in gastric cancer." (PMID 41008630, 2025). "AARS1 could catalyse YAP‐K90la and TEAD1‐K108la, core components of the Hippo pathway, enhancing their interaction and ultimately exacerbating the malignancy of gastric cancer." (PMID 40984037, 2025). "Similarly, activation of the TEAD1 signaling pathway promotes malignant phenotypes in gastric cancer cells." (PMID 40539054, 2025). "However, overexpressed TEAD1 is only observed in two subtypes of gastric cancer, Epstein–Barr virus-positive subtype and microsatellite instability subtype." (PMID 35602596, 2022). "Another study found that AARS1 lactylates the YAP/TEAD1 complex in gastric cancer (GC) cells using the same catalytic mechanism." (PMID 41373440, 2025). "To further confirm the role of YAP1 in the regulation of AGK in gastric cancer cells, we associated AGK expression with other YAP1‐related proteins in gastric cancer tissue samples and found that AGK expression was also associated with the expression of TEAD1, TEAD2 and TEAD4." (PMID 32827244, 2020). "Increased TEADs (TEAD1-4) mRNA expressions were significantly correlated with overall survival (OS), progression-free survival (PFS), and post-progression survival (PPS) in gastric cancer (GC) patients." (PMID 38607003, 2024). "We used this dataset to evaluate the expression patterns of YAP1, STAT3, IL11, IL6, TEAD1, IL6ST, and IL11RA in gastric cancer patients within the four TME subtypes." (PMID 37957015, 2024). "It should be noted that, both TEAD1 and TEAD4 are overexpressed in gastric cancer TCGA cohort in this study." (PMID 35602596, 2022). "FZD5, ELF3, TEAD1 and SNAI2 expression in 55 gastric cancer tissues was detected by immunohistochemistry." (PMID 33618713, 2021). "However, TEAD1 expression was highest in GS tumors and significantly higher in chromosomal instability tumors when compared with EBV and microsatellite instability gastric cancer subtypes." (PMID 37957015, 2024).
breast carcinoma (15 papers, 2012 to 2023). "Phosphofructokinase (PFK1), a key enzyme of glycolysis, binds TEAD1 in the presence of glycolysis, stabilizing YAP/TAZ and TEAD1, and thus promoting the malignant behavior of breast cancer (BC) cell." (PMID 37799806, 2023). "Taken together, these results therefore suggested that YAP1/TEAD1-2 can affect tumor growth in HER2-positive breast cancer, likely by promoting cell proliferation." (PMID 32365528, 2020). "Tead1 germline mutant embryos presented decreased percentage of myocardial cells in S phase as was also seen in breast cancer cells, wherein knockdown of all Tead family members led to similar cell cycle changes." (PMID 30811446, 2019). "Correspondingly, we identified TEAD1 as the primary TEAD family member expressed in breast cancer cells." (PMID 28733631, 2017). "In this study, we investigated the expression and roles of TEADs in breast cancer and found that TEAD1 and TEAD4 are widely expressed in several breast cancer cell lines, particularly TNBC lines." (PMID 25970772, 2015). "We first examined the protein expression levels of TEAD1–4 in two immortalized breast epithelial cell lines and six breast cancer cell lines via Western blotting to explore the role of TEADs in breast cancer." (PMID 25970772, 2015). "TEAD1 has been found either upregulated, for instance in prostatic or pancreatic cancers, or conversely decreased in bladder or breast cancer, for example (as reported by the ONCOMINE database)." (PMID 23029054, 2012). "Among four members of TEAD, TEAD1 and TEAD4 are widely expressed in breast cancer cell lines, especially highly expressed in TNBC cell lines." (PMID 25970772, 2015). "TEAD1 is the key regulator of Hippo signal pathway, and several studies suggested that it functions as a transcription factor participating in the transcription of GLUT1 in laryngeal squamous cell carcinoma, breast cancer and T-cell lymphoma." (PMID 37723874, 2023). "In the presence of glycolysis, phosphofructokinase-1 (PFK1), a key glycolytic enzyme, could bind with TEAD1 to stabilize a PFK1-TEAD1-YAP protein complex in the nucleus, revealing a molecular mechanism for PFK1-induced tumor malignant in breast cancer." (PMID 35012640, 2022). "Using an unbiased global transcriptome and proteomic analysis of HER2-positive breast-cancer cells, we propose a new model in which acquired resistance to trastuzumab may be mediated by the increased activity of the YAP1/TEAD1-2 complex." (PMID 32365528, 2020). "These authors have shown that YAP1 and TEAD1 are involved in transcriptional control of the glucose transporter GLUT1, whereas knockdown of YAP1 inhibited glucose consumption, and lactate production of breast cancer cells, overexpression of GLUT1 restored glucose consumption and lactate production." (PMID 33427197, 2021). "Our examination showed that both TEAD1 and TEAD4 are widely expressed in breast cell lines, though the expression levels were higher in two basal immortalized breast epithelial cell lines and two basal TNBC cell lines as compared to ERα+ or HER-2+ breast cancer cell lines." (PMID 25970772, 2015).
heart failure (13 papers, 2014 to 2025). Inability of the heart to pump blood at an adequate rate to meet tissue metabolic requirements. "In the heart, loss of either YAP or TEAD1 decreased CM survival and caused heart failure, probably due to the downregulation of anti-apoptosis genes and disruption of mitochondria structure." (PMID 34206257, 2021). "Many of the markers often associated with heart failure were differentially changed with Tead1 deletion." (PMID 30811446, 2019). "RNA isolated from the ventricles from 1-day-old Tead1-cKO and control flox littermate pups was assayed for molecular markers associated with heart failure and the cardiac fetal program." (PMID 30811446, 2019). "Therefore, further studies are needed to identify the proper dosage to optimally alter the YAP/TEAD1 signaling pathway and treat heart failure that is caused by LMNA-related DCM." (PMID 37058558, 2023). "In addition, absence of upregulation of βMHC (Myh7), a fetal gene program marker of heart failure, in the failing hearts of the Tead1-cKO mice demonstrates requirement of Tead1 for heart failure-associated fetal program increase in βMHC." (PMID 30811446, 2019). "Taken together, these data demonstrate that Tead1 is critical for the proliferation of CM perinatally via regulation of the levels of many critical cell cycle markers in all phases of cell cycle and its perinatal loss leads to heart failure and DCM." (PMID 30811446, 2019). "Meanwhile, administration of a necroptosis inhibitor, necrostatin-1, effectively rescued heart failure induced by TEAD1 deletion." (PMID 39781453, 2025). "While it has been shown that its transcriptional activity through TEAD1 regulates SERCA2a expression and is necessary for adult heart function, its overexpression leads to heart failure through the repression of Serca2a expression." (PMID 41213910, 2025). "The results provide novel evidence that the SUMOylation of TEAD1 is a promising therapeutic strategy for hypertrophy‐related heart failure." (PMID 38225750, 2024). "Immunoblot assays showed that TEAD1 protein levels were dramatically increased in patients with heart failure compared to those in healthy controls." (PMID 38225750, 2024). "Consistent with the changes in protein levels, the mRNA level of TEAD1 was also upregulated in individuals with heart failure compared to controls." (PMID 38225750, 2024). "First, the expression level of TEAD1 in patients with heart failure, mice, and cardiomyocytes is investigated." (PMID 38225750, 2024). "The overexpression of the TEAD1 gene can induce the characteristics of cardiac remodeling related to cardiomyopathy and heart failure." (PMID 36980284, 2023). "We previously found that the primary interaction partner of TEAD1 is YAP in the neonatal heart and that overexpressing a K225R-mutated VGLL4 in the neonatal heart disrupted the TEAD1–YAP interaction, suppressed CM proliferation, and caused heart failure." (PMID 36139407, 2022). "As mentioned in Section “Role of Hippo–YAP1/TAZ Signaling and Its Differentiation Output in Heart Development,” YAP1/TEAD1-OSM feedback cycle exacerbates heart failure and the progression of diabetic cardiomyopathy in HFD-fed mice following TAC." (PMID 32390875, 2020). "Although TEAD-1 knockout mice show embryonic lethality, mice in which TEAD-1 was conditionally overexpressed in cardiomyocytes exhibited heart failure with increased MYH7 gene expression." (PMID 24781449, 2014). "In later periods, persistent activation of YAP1 produces cardiac dysfunction and heart failure, which may be partly caused by the YAP1/TEAD1–OSM positive feedback loop and cardiac remodeling." (PMID 32390875, 2020). "Importantly, overexpression of Tead1 in the mouse heart induced cardiomyopathy and heart failure, suggesting that Tead1 is vital for proper heart development." (PMID 31632964, 2019).
heart failure (continued). "However, in the Tead1-depleted cardiomyocytes, ex vivo (ex vivo Tead1 deletion in neonatal cardiomyocytes) and in vivo (Tead1-cKO) models, both α-MHC and β-MHC are significantly repressed despite the evident heart failure phenotype in vivo." (PMID 30811446, 2019). "None of the Tead1-cKO mice survived beyond postnatal day 9 and died of severe heart failure." (PMID 30811446, 2019).
ovarian carcinoma (9 papers, 2014 to 2026). A malignant neoplasm originating from the surface ovarian epithelium. "Supporting these findings, we found a strong positive correlation between ZDHHC15 and TEAD1 expression in breast, liver, and ovarian cancers by mining the RNA‐sequencing data across different cancer types in The Cancer Genome Atlas (TCGA)." (PMID 39686664, 2025). "On the other hand, TEAD1 significantly affected overall survival (OS) of ovarian cancer patients based on TCGA database 26, so we further took TEAD1 as representative to verify its possibility as the putative miR-6836 upstream regulator." (PMID 37416779, 2023). "In ovarian cancer initiated cells, TEAD1 and TEAD4 were found to be expressed at significantly higher levels than in differentiated ovarian cancer cells." (PMID 31718559, 2019). "TEAD1/2 enhanced mesothelin transcription which was frequently overexpressed in pancreatic and ovarian cancer." (PMID 29050244, 2017). "Moreover, the increase of p-YAP expression and decrease of p-gp and TEAD1 expression in the two ovarian cancer cells were reversed by a co-treatment with EMSO+PTX." (PMID 31718559, 2019). "Correlation analysis results showed that YAP and pYAP were positively correlated with TEAD1-4 expression, and were most closely correlated with TEAD4 expression.An association analysis using 45 ovarian cancer patient samples was done in which we ranked Kaplan-Meier survival estimates." (PMID 24622501, 2014). "Therefore, we speculate that modulating YAP and TEAD1 activities may be an effective strategy to prevent the PTX-resistance in ovarian cancers." (PMID 31718559, 2019). "The TEAD1 gene is a co-activator of YAP, and both are required to maintain stemness and chemoresistance in ovarian cancer-initiating cells." (PMID 36607962, 2023). "In ovarian cancer initiated cells (OCICs), TEAD1, TEAD3 and TEAD4 were found to be expressed at significantly higher levels than in differentiated ovarian cancer cells." (PMID 26805820, 2016). "CDR3β peptides identified in the specificity group can recognize cells with the TEAD1 neoantigen; therefore, CD8+ cells in patients harboring the receptors can target ovarian cancer-initiating cells for destruction, reducing chemoresistance and the probability of recurrence." (PMID 36607962, 2023).
prostate carcinoma (9 papers, 2008 to 2026). A carcinoma that arises from epithelial cells of the prostate gland. "Importantly, Yes-associated protein (YAP) is a TEAD1 co-activator localised to basal cell nuclei in normal prostate and overexpressed in prostate cancer." (PMID 19002168, 2008). "TEAD1 expression levels are higher in PC3 cells and tissue specimens, which is associated with poor prognosis in prostate cancer patients." (PMID 32066485, 2020). "In both PC3 cells and patients’ samples, TEAD1 showed a high expression level, which was correlated with poor prognosis in prostate cancer patients." (PMID 26805820, 2016). "For example, high expression levels of TEAD1 correlate with poor clinical outcomes in prostate cancer, while knockdown of TEAD1 decreased cell growth in PC3 and disrupted acinar formation in a 3D culture system of RWPE1." (PMID 25970772, 2015). "In agreement with our results, it has been shown that in cancers where TEAD1 is overexpressed, such as in prostate cancers, Livin is also up-regulated." (PMID 23029054, 2012). "Our data identify TEAD1 as a transcriptional regulator associated with the NEPC state and suggest a role for TEAD1-linked transcriptional and post-transcriptional mechanisms in prostate cancer lineage plasticity." (PMID 42217442, 2026). "TEAD1/4 overexpression was considered as prognostic marker for prostate cancer." (PMID 29050244, 2017). "This suggests that while high levels of either TEAD1 or c-Cbl are indicative of equally poor prognosis, they may identify somewhat different tumour types, supporting the observation that prostate cancer is a truly heterogeneous disease." (PMID 19002168, 2008). "Furthermore, an increased staining intensity for both c-Cbl and TEAD1 was observed in prostate cancer samples on a TMA." (PMID 19002168, 2008). "As both TEAD1 and c-Cbl are highly expressed in aggressive prostate cancers, it could be possible that these aggressive cancers, and hence PC3, are dependent on these genes, directly or indirectly, for their proliferative capacity." (PMID 19002168, 2008). "In addition, when a prostate cancer patient is detected with a high TEAD1 expression, the clinical outcome of this patient might be poor." (PMID 26805820, 2016). "This study demonstrates the role of YAP1, TEAD1 and SRC in the conversion of NFs to CAFs in prostate cancer." (PMID 32066485, 2020). "As knockdown of TEAD1 led to a reduced proliferation in PC3 cells, it is possible that an increased expression of both TEAD1 and YAP could stimulate proliferation in prostate cancer." (PMID 19002168, 2008).